ENSG00000268193 (novel transcript)
Gene: Protein-coding gene on chromosome 19 (18,907,013 to 18,934,397, reverse strand). Ensembl gene ENSG00000268193.
Genetic constraint (gnomAD): Missense variants: 93 observed, 81.68 expected, observed/expected ratio (o/e) 1.14, 90% interval 0.96 to 1.35. Synonymous variants: 52 observed, 36.44 expected, observed/expected ratio (o/e) 1.43, 90% interval 1.14 to 1.78.